ADAMTS1 (ADAM metallopeptidase with thrombospondin type 1 motif 1)
Diseases named in the same sentence as ADAMTS1 in open-access papers (continued):
Sharing a sentence is not in itself a finding about the gene and the disease.
tumor (continued). "Again, a clear impairment of tumor progression, in this case affecting the metastatic process, appeared dependent of the presence of Adamts1 in the stroma." (PMID 27120788, 2016). "Numerous studies report changes in ADAMTS-1 mRNA and protein levels in tumor progression in the prostate, liver and mammary gland." (PMID 27764205, 2016). "Our results showed the strong expression of CD147, as well as ADAMTS1 and 9 within KS tumor tissues from all the patients (CF0002, JG004 and XX007)." (PMID 26675551, 2016). "In fact we even detected that Adamts1 tumor expression suffered an induction in the ATS1-KO mice, probably related with its regulation by hypoxia." (PMID 27120788, 2016). "In particular, elevated ADAMTS1 promotes pro-tumorigenic changes such as increased tumor cell proliferation, decreased apoptosis and altered vascularization." (PMID 26675551, 2016). "Here, to examine the contribution of ADAMTS1 by different cell compartments, we carried out syngeneic tumor experiments in wild type and ADAMTS1 KO mice." (PMID 27120788, 2016). "Genetic deletion of ADAMTS1 in the host microenvironment resulted in a drastic decrease of tumor growth and metastasis." (PMID 27120788, 2016). "Immunoblot results confirmed the higher levels of CD147, ADAMTS1 and 9 expression in tumor lysates from mice with n-siRNA than those from mice with CD147-siRNA, demonstrating the successful silencing of CD147 and downstream ADAMTSs in vivo." (PMID 26675551, 2016). "This suggests that the inability of shNFAT1-4T1 cells to degrade the extracellular matrix, an essential process for tumor cells to invade and disseminate, is associated with the decreased NFAT1-dependent expression of ADAMTS1." (PMID 25719243, 2015). "Tumors in mice displayed reduced cleaved versican and increased presence of cytotoxic immune cells, suggesting that ADAMTS1 creates a tumor-promoting microenvironment in the mammary gland." (PMID 26025392, 2015). "It has been shown that the upregulation of ADAMTS1 promotes pro-tumorigenic changes such as an increase in tumor cell proliferation, inhibition of apoptosis, and alteration of vascularization status." (PMID 25285958, 2014). "Our analysis from the TCGA database suggest a significant inverse correlation between hHSS1 and ADAMTS1 expression, which is consistent with a role of hHSS1 in inhibition of tumor growth, progression and metastasis." (PMID 25481245, 2014). "Despite the suggested roles for ADAMTS-1 in tumor invasion and metastasis, the effects of this molecule during cancer progression remain controversial." (PMID 23289900, 2013). "Immunohistochemistry (IHC) was carried out in samples from normal tissue; breast cancer tumors of grade IIA, IIB, IIIA and IIIC; and metastatic lymph nodes, and we evaluated ADAMTS-1 expression in the tumor cell cytoplasm and the surrounding stroma." (PMID 23289900, 2013). "We then assessed differences in staining intensity with regard to the ADAMTS-1 distribution among tumor cells or stroma." (PMID 23289900, 2013). "The extracellular protease ADAMTS1 promotes some tumor cells to mimic an endothelial-like phenotype." (PMID 24009721, 2013). "Angiogenesis is a critical event during implantation and tumour invasion, and ADAMTS-1 and -8 have been assigned this function in several kinds of tumours, but the expression and regulation of ADAMTS-8 in reproductive tissues have not been reported." (PMID 23947778, 2013). "The prostate stromal microenvironment has been postulated to limit tumor growth through the up-regulation of genes inhibiting proliferation and angiogenesis, including ADAMTS1." (PMID 24260246, 2013). "In other experimental tumor models, ADAMTS1 also presented a complex and often contradicting role in different studies." (PMID 24213506, 2012). "In yet another scenario, ADAMTS1 increased fibrosarcoma tumor growth rate in an angiogenesis-independent manner, with tumor cells acquiring a endothelial-cell like phenotype possibly through a vascular mimicry mechanism." (PMID 24213506, 2012).
tumor (continued). "In line with the differential expression of ADAMTS1 in several cancer types, ADAMTS1 seems to promote tumor growth and metastasis in some cancers while in others its expression is down-regulated implicating a tumor suppressor role." (PMID 24213506, 2012). "On the other hand, ADAMTS1 acts as a tumor promoting factor in androgen-dependent LnCAP tumors, as down-regulation of ADAMTS1 results in reduced tumor growth in these tumors." (PMID 24213506, 2012). "ADAMTS1/METH-1 was first discovered in mouse by differential display from colon 26 adenocarcinoma cachexigenic tumor cell lines." (PMID 24213506, 2012). "Instead, we found that ADAMTS1 expression was inversely related to the total levels of TSP1 in the tumor xenografts." (PMID 20546609, 2010). "In contrast, increased levels of ADAMTS1 in LNCaP-19 resulted in markedly slower tumor establishment." (PMID 20546609, 2010). "ADAMTS1 has been reported to efficiently inhibit tumor growth and metastasis in different experimental cancer models by blocking angiogenesis, and decreased expression of ADAMTS1 has been reported in human malignancies." (PMID 20546609, 2010). "ADAMTS1 is believed to be an inhibitor of both angiogenesis and endothelial proliferation, features commonly activated in cancer, as a tumor must turn on angiogenesis in order to grow larger than 1–2 mm3." (PMID 19117505, 2008). "ADAMTS-1 immunoreactivity was mostly seen in normal epithelial bronchial cells in control lung tissues as well as in normal bronchi surrounding tumour nodules in diseased lung." (PMID 16495931, 2006). "The activation status of ADAM-12 and ADAMTS-1 in tumours and corresponding control tissues was investigated by Western blotting." (PMID 16495931, 2006). "Reportedly, ADAMTS1 promotes tumor formation and metastasis in renal and breast cancers." (PMID 40867252, 2025). "Our investigation interestingly highlighted that ADAMTS1 may act, in the context of PCa tissue, as a tumour suppressor or as a pro-tumorigenic factor in agreement with previous experimental evidence." (PMID 38254687, 2024). "Moreover, we observed the effect of ADAMTS1 on NSCLC cells in vivo by constructing a tumor metastasis model in nude mice with NSCLC." (PMID 36947712, 2023). "In contrast, ADAMTS1 may have a suppressive activity in tumor cell growth and progression in protease-dependent and -independent manners." (PMID 35625488, 2022). "Through next-generation sequencing (NGS), bioinformatic technologies, and functional assays, the ADAMTS1 in advanced LUAD might play a role in the tumor progression and metastasis by changing the host microenvironment." (PMID 35625488, 2022). "Thus, full-length ADAMTS-1 has been demonstrated to promote the progression of tumor angiogenesis, but the truncated forms were able to suppress angiogenesis and tumor growth." (PMID 36144730, 2022). "All of the results above indicate that ADAMTS1 has a tumor suppressive role on LUAD." (PMID 35625488, 2022). "Because ADAMTS1 is an extracellular protease, which is required for a balanced immune cell repertoire and tumor inflammatory response, we assessed the role of ADAMTS1 in the tumor immune microenvironment using the Timer 2.0 website." (PMID 35625488, 2022). "The majority focused on ADAMTS-1, providing evidence of a tumor-suppressing function." (PMID 33808504, 2021). "Furthermore, there was co-expression among the ADAMTS1–8 genes in the GC tumor tissues, demonstrating that the genes are positively correlated with GC development (Pearson correlation coefficient range: 0.11–0.69; P<0.05)." (PMID 33851708, 2021). "As we are interested in the acquisition of endothelial-like properties by GBM cells, we found the positive correlation of ADAMTS1 with endothelial markers very encouraging, remarking that these genes are not discovered just in genuine endothelium, but they are also expressed in tumor cells." (PMID 33396280, 2020).
tumor (continued). "Indeed, when we analyzed ADAMTS1 expression data considering different stages of tumor progression, we observed a clear tendency for ADAMTS1 to be more expressed at early phases (identified here with stage IIA) and decreases with higher grades." (PMID 32230715, 2020). "Indeed, although ADAMTS1 expression appears increased with tumor progression, the dynamism of the TME would involve new constituents that still require to be deeply investigated." (PMID 33396280, 2020). "Notably, the performance of xenograft assays in distinct mouse models supported the pro-tumorigenic effects of ADAMTS1 in UVM, revealed mainly by the significant blockade of tumor development when ADAMTS1 was inhibited." (PMID 32230715, 2020). "ADAMTS1 affects the tumor microenvironment in a manner unrelated to angiogenesis." (PMID 32102222, 2020). "Indeed, our experiments show that ADAMTS1 is also relevant to the stemness capacities of such tumor cells in both in vitro and in vitro approaches, with strong consequences for tumor growth." (PMID 32230715, 2020). "Very importantly, the evaluation of ADAMTS1 in this tumor collection allowed us to observe its higher expression levels at early phases of this malignant tumor, and then appeared downregulated as the disease progressed to advanced stages, in harmony with our results on stemness features." (PMID 32230715, 2020). "Specifically, ADAMTS1 increases tumor growth rate by inhibiting Matrigel and fibrin gel function." (PMID 32102222, 2020). "All these data confirmed the relevance of ADAMTS1 for tumor development." (PMID 32230715, 2020). "ADAMTS1 was identified as an epigenetically deregulated gene in CRC, and it was suggested that ADAMTS1 could play an important role in tumor growth and metastasis." (PMID 31340858, 2019). "In addition, ADAMTS-1 can block tumor growth in vivo by sequestering VEGF165 through its carboxy-terminal region, which contains the final two TSP-1 motifs." (PMID 31508361, 2019). "In addition, ADAMTS1 was described as having tumor-protective effects and angiogenesis inhibitory enzyme due to its capacity to restrain endothelial cell proliferation." (PMID 30679934, 2019). "Alongside, our investigation includes B16F1 tumour-bearing Ats1-KO mice, allowing the identification of previously unknown activities of ADAMTS1 in immune organs." (PMID 30166561, 2018). "In particular, we show that miR-548k regulates different hallmarks of cancer, including cell proliferation, migration, invasion, and tumor microenvironment remodeling through combinatorial regulating of multiple oncogenic routes, involving the ADAMTS1-VEGFC-VEGFR3 pathway and KLF10-EGFR axis." (PMID 30131072, 2018). "Since some ADAMTSs (e.g. ADAMTS-1 and -8) have anti-angiogenic activities that contribute to the inhibition of cancer development, we thus examined the relevance of Adamts18 with tumor angiogenesis." (PMID 28145888, 2017). "For example, ADAMTS1 was found to be significantly over-expressed in clonal populations of highly metastatic cells to bone, and other authors have shown that its contribution to tumor development involved an induction of stroma remodeling." (PMID 27120788, 2016). "Also, full length ADAMTS 1 increases tumor cell proliferation rates and accelerates tumor development through the activity of its metalloproteinase domain." (PMID 26916548, 2016). "The use of a syngeneic tumor model with the ADAMTS1 KO mice, in combination with human xenografts and ex-vivo studies, allowed us to discriminate between the functional contribution of ADAMTS1 provided by tumor or stromal elements." (PMID 27120788, 2016). "Though originally reported for ADAMTS1 and 8, many ADAMTSs have proved to be anti-angiogenic, a property that may contribute to their tumor-suppressive actions." (PMID 26025392, 2015). "In addition, up-regulation of ADAMTS1 in tumors participate in the remodeling of the peritumoral stroma, tumor growth and metastasis." (PMID 25481245, 2014).
tumor (continued). "However, high-grade tumors (IIIA and IIB) exhibited a trend towards decreased ADAMTS-1 expression in comparison to the lower tumor grades." (PMID 23289900, 2013). "Our findings indicate that the effects of ADAMTS-1 in tumor invasiveness may be related to the availability of VEGF." (PMID 23289900, 2013). "Therefore, we considered tumor stage in our analysis and also evaluated the expression of ADAMTS-1 in the tumor stroma, which was reduced in higher-staged tumors." (PMID 23289900, 2013). "Thus, they proposed that the proteolytic status of ADAMTS1 determines its net effect on tumor metastasis." (PMID 24213506, 2012). "Moreover, ADAMTS1 has demonstrated angiogenesis dependent and angiogenesis-independent effects on tumor growth and metastasis from different studies." (PMID 24213506, 2012). "Conceivably, the local microenvironment of the particular tumor, the level of ADAMTS1 expression, the type of substrates present in the local ECM, and the tissue-specific characteristics of tumor cell types all contribute to the net influence of ADAMTS1 in particular types of tumor." (PMID 24213506, 2012). "In NSCLC however, ADAMTS1 is down-regulated via promoter methylation and thus could be acting as a tumor suppressor in this cancer." (PMID 24213506, 2012). "ADAMTS1 is also involved in such a tumor-stromal interaction." (PMID 24213506, 2012). "Several reports suggest a role for ADAMTS1 in promoting tumor cell invasion." (PMID 24213506, 2012). "Interestingly, we found that modified expression of ADAMTS1 markedly altered the blood vessel morphology in these tumor xenografts, while the number of blood vessels was unaffected." (PMID 20546609, 2010). "In addition, the tumor growth was differently affected by ADAMTS1 in androgen-dependent LNCaP and androgen-independent LNCaP-19 tumors." (PMID 20546609, 2010). "However, the involvement of ADAMTS1 in tumor progression is complex, with data also describing ADAMTS1 as a tumor promoting factor." (PMID 20546609, 2010). "Moreover, upregulation of ADAMTS1 inhibited tumor growth of LNCaP-19, as evidenced by delayed tumor establishment." (PMID 20546609, 2010). "However, downregulation of ADAMTS1 in LNCaP resulted in a reduced tumor growth rate, suggesting that ADAMTS1 rather is a tumor promoting factor in androgen-dependent LNCaP tumors." (PMID 20546609, 2010). "In this study, re-expression of ADAMTS1 in LNCaP-19 greatly delayed tumor establishment, indicating that ADAMTS1 actually might function as a tumor suppressor of androgen-independent prostate tumors." (PMID 20546609, 2010). "In contrast, downregulation of ADAMTS1 in LNCaP resulted in reduced tumor growth rate." (PMID 20546609, 2010). "However, some studies have reported ADAMTS1 as a tumour suppressor." (PMID 40864881, 2025). "Notably, ADAMTS1 expression was also inversely correlated with the accumulation of immunosuppressive myeloid-derived suppressor cells and regulatory T cells, implying the downregulated ADAMTS1 mediated immune adjustment to fit the tumor survival disadvantages in LUAD patients." (PMID 35625488, 2022). "However, controversy regarding cancer and ADAMTS1 exists, and its role is still under debate, since it could act as either a tumor suppressor or an oncogene depending on the cellular context or specific cancers." (PMID 35625488, 2022). "Increased mRNA expression of ADAMTS1, CCL19, and CXCL12 was associated with peritoneal metastasis, suggesting that these genes related to the tumor microenvironment may play a significant role in tumor progression." (PMID 34830815, 2021). "Importantly, the immune system of NSG mice displays a stronger defect than SwN, so the distinct ability of ATS1-KO cells to initiate tumor progression in these two models could be related with an immunomodulatory role already attributed to ADAMTS1." (PMID 32230715, 2020).
tumor (continued). "Collectively, our results reveal that overexpression miR-548k may promote lymphangiogensis and lymphatic metastasis of ESCC through modulating the conversation between tumor cells and lymphatic endothelial cells in tumor microenvironment via ADAMTS1/VEGFC/VEGFR3 cascade." (PMID 30131072, 2018). "Further, induction of A disintegrin and metalloproteinase with thrombospondin-type repeats-1 (ADAMTS1) has been related to angiogenic sprouting during wound healing, and elevated expression of heparanase (HPSE) in patients is associated with high levels of tumor-associated angiogenesis." (PMID 26393803, 2015). "Hence, fibulin-1 could potentiate degradation of ECM components by ADAMTS-1 and thereby facilitating tumor progression." (PMID 24457941, 2014). "However, in androgen-independent LnCAP-19 tumors, expression of ADAMTS1 delays tumor establishment." (PMID 24213506, 2012). "Thus it could be seen that ADAMTS1 could both induce as well as be induced by stromal components, exhibiting an excellent example of tumor-stroma crosstalk." (PMID 24213506, 2012). "In addition, TSP1 levels in the tumor xenografts were inversely related to ADAMTS1 expression." (PMID 20546609, 2010). "Moreover, the effect of ADAMTS1 on tumor growth was different in LNCaP and LNCaP-19." (PMID 20546609, 2010). "Results of the IHC analysis revealed the upregulation of L1CAM in tumor tissues from metastatic LNs where ADAMTS1 was overexpressed and the downregulation of L1CAM in tumor tissues from metastatic LNs where ADAMTS1 was knocked down." (PMID 38263290, 2024). "Knockdown of ADAMTS1 in OSCC cells led to a decrease and its overexpression led to an increase in cell-invasive abilities in vitro as well as tumor growth and lymph node (LN) metastasis in OSCC xenografts." (PMID 38263290, 2024). "MXRA8 appears to regulate these processes by altering genes like ADAMTS1 and TIE1 that influence the tumor microenvironment." (PMID 37762032, 2023). "This study investigates our DNA methylation-based PC biomarker panel (ADAMTS1, BNC1, and CACNA1G genes) in differentiating IPMN-advanced neoplasia from IPMN-LGDs." (PMID 36803844, 2023). "Immunohistochemistry of ADAMTS1, DSC1, RNF39, CD3 and LDB3 was performed to evaluate protein expression in tumor cells." (PMID 36333410, 2022). "By contrast, expression of each of ADAMTS1, ADAM19, ADAMTS13, and ADAMTS17 in tumor tissue was 0.75-fold lower than that in NCL." (PMID 36230656, 2022). "During the pathological process, ADAMTS-1 can cleave or induce the release of proangiogenic factors (IGFBP2, HB-EGF, AR) and degrade ECM components, such as versican, to facilitate tumor invasion." (PMID 36338393, 2022). "Alternatively, various factors enriched in EVs of hypoxic cancer cells have been shown to limit the infiltration of immune cells into the tumor, including IGFBP-3, TSP-1, and a disintegrin and metalloprotease with thrombospondin motif 1 (ADAMTS1)." (PMID 36010994, 2022). "We found that CYP7A1, GINS2, and PDLIM3 were significantly up-regulated, and MYC, MAMDC4, ADAMTS1, THBS1, and RASD1 were significantly down-regulated in HCC tumor samples compared to normal samples." (PMID 34777484, 2021). "We found that CYP7A1, GINS2, and PDLIM3 were significantly up-regulated, and MYC, MAMDC4, ADAMTS1, THBS1, and RASD1 were significantly down-regulated in HCC tumor samples compared with normal samples using the TCGA dataset." (PMID 34777484, 2021). "A study published in 2019 showed that the methylation status of ADAMTS1 and BNC1 in cell-free DNA is highly sensitive and specific to the early diagnosis of PC, these epidemiological markers varying with tumor stage." (PMID 33114412, 2020).